SPG11 (SPG11 vesicle trafficking associated, spatacsin)
Diseases named in the same sentence as SPG11 in open-access papers (continued):
Sharing a sentence is not in itself a finding about the gene and the disease.
Spastic paraplegia (23 papers, 2015 to 2025). Complete loss of the ability to move the lower limbs accompanied by spasticity of the lower limbs. "Pathogenic variants in SPG11 are associated with spastic paraplegia with mild intellectual disability (OMIM #604360), which is in keeping with the phenotype of affected individuals in this family." (PMID 40730687, 2025). "Additional research will determine if SPG11 variants are as commonly present in Pakistani patients with spastic paraplegia as observed in different global populations." (PMID 38906889, 2024). "For P41, the possibility of spastic paraplegia was excluded, and we suspected that the SPG11 p.Q1624X mutation is a novel PSIS pathogenic gene involved in nervous system development." (PMID 32864857, 2020). "In the past, complex recessive spastic paraplegias have been frequently associated with SPG11 mutations but also with defects in SPG15, SPG7 and a handful of other rare genes." (PMID 27544499, 2016). "Mutations in SPG11 comprise a major cause of spastic paraplegia with a thin corpus callosum." (PMID 32864857, 2020). "In this regard, patients diagnosed with mild-to-moderate SPG11 spastic paraplegia typically show minimal corpus callosum thinning while severe SPG11 patients had more severe thinning as well as cerebral atrophy." (PMID 37510225, 2023). "Here, we describe the clinical and pathological characteristics of an autopsied patient with spastic paraplegia with a TCC and a homozygous splice site variant in the SPG11 gene (NM_025137.3: c.4162–2A > G)." (PMID 34979968, 2022). "In four patients, rare heterozygous RDVs were detected in other neurodegeneration-associated genes, such as PRKN (PD), LRRK2 (PD), PARK7 (PD), C19ORF12 (NBIA), SPG11 (Spastic paraplegia-SP/ALS), and PSAP (Metachromatic leukodystrophy-MLD)." (PMID 35752680, 2022). "In this study, we performed a custom-designed panel sequencing by next-generation sequencing in four sporadic patients with spastic paraplegia and TCC, and identified novel as well as reported SPG11 mutations." (PMID 33430805, 2021). "No cases of spastic paraplegia have been reported to be caused by monoallelic recessive SPG-11 or SYNJ1 mutations." (PMID 37510225, 2023). "Therefore, we suggest that the genetic interaction and protein haploinsufficiency of SPG11 and SYNJ1, both proteins implicated in common biochemical pathways, cause clinical spastic paraplegia of late onset." (PMID 37510225, 2023). "SPG48 patients have some clinical features similar to those of SPG11 or SPG15 patients, including spastic paraplegia, retinal abnormalities, and parkinsonism." (PMID 38035585, 2023). "Cysts are very rarely observed in spastic paraplegia individuals except SPG4 (posterior fossa findings) and SPG11." (PMID 32166732, 2020). "Eventually, we further validated the cellular changes in fibroblasts of two major spastic paraplegia (SPG) patients (SPG4 and SPG11) in vitro." (PMID 29980238, 2018). "In conclusion, we report for the first time a known heterozygous recessive SPG11 c.1951C>T mutation and a not-reported heterozygous recessive SYNJ1 c.2614G>T mutation in a European Caucasian patient with clinical spastic paraplegia of late onset." (PMID 37510225, 2023). "Thus, our findings provide new insights into both the function of the AP-5 AP-5/SPG11/SPG15 in normal cells and why its absence leads to spastic paraplegia and could potentially open up new therapeutic approaches, such as the use of autophagy regulators." (PMID 33464297, 2021).
Parkinsonism (17 papers, 2012 to 2025). Characteristic neurologic anomaly resulting from degeneration of dopamine-generating cells in the substantia nigra, a region of the midbrain, characterized clinically by shaking, rigidity, slowness of movement and difficulty with walking and gait. "Patients with SPG11 homozygous mutations can have tremor or parkinsonism, mostly in the later stages of their disease, which are mostly L-dopa responsive." (PMID 38153678, 2024). "Kara et al5 assessed 30 cases of SPG11, five of whom had parkinsonism, and three of these five reported benefit associated with levodopa." (PMID 37635774, 2023). "Dopa-responsive dystonia associated with spasticity and parkinsonism was present in a patient with SPG11, who soon developed a wearing-off phenomenon and levodopa-induced dyskinesias." (PMID 38035585, 2023). "Conversely, SPG11 mutations were more frequently associated with consanguinity (OR = 4.1), parkinsonism (OR = 7.8), dystonia (OR = 5.4), peripheral neuropathy (OR = 26.9), and cognitive dysfunction (OR = 34.5)." (PMID 36441344, 2023). "The second study described a subject with HSP and parkinsonism harboring biallelic mutations in the SPG11 gene; the patient's parkinsonian features were responsive to 300 mg/day oral L-Dopa." (PMID 30723448, 2019). "Additional evidence indicates that mutation of SPG11 is a rare cause of early-onset levodopa-responsive parkinsonism with pyramidal signs." (PMID 22623900, 2012). "Two patients, of Turkish descent, from the same consanguineous family, were affected with SPG11 in association with unusual early-onset parkinsonism that occurred during the very early stages of SPG11 in both patients." (PMID 22623900, 2012). "Despite its rarity and variability, SPG11 shares common pathogenic mechanisms with other neurodegenerative diseases such as Alzheimer’s and Parkinson’s, including mitochondrial dysfunction, oxidative stress, inflammation, and alterations in lipid metabolism and gut microbiota." (PMID 41228418, 2025). "SPG11 has been linked with parkinsonism or dystonia-parkinsonism." (PMID 33646413, 2021). "Finally, Parkinsonism, cerebellar ataxia, and even multiple sclerosis‐like symptoms have been reported in some patients with SPG11 mutations, thus adding to the clinical heterogeneity that is associated with mutations in SPG11." (PMID 32383541, 2020). "Patients with SPG11-related parkinsonism typically experience a more severe disease progression and an earlier onset compared to those without parkinsonism." (PMID 37648940, 2023). "SPG11 share an overlapping phenotype with SPG15.22Levodopa-responsive parkinsonism has been described as the first symptom of the disease both in patients with SPG11 and with SPG15." (PMID 38035585, 2023). "A case report published by Paisán‐Ruiz et al7 describes one further case of SPG11 with levodopa‐responsive parkinsonism and bilateral decreased striatal uptake on DaTscan." (PMID 37635774, 2023). "Another 2018 study of 22 patients with SPG11 revealed parkinsonism in six (27.3%) of mainly rigid‐akinetic type, similar to our patient's presentation, with rest tremor present in only three patients." (PMID 37635774, 2023). "SPG11 was the most prevalent genotype in individuals presenting with action tremor (32.4%), dystonia (27.3%), parkinsonism (35.6%), rest tremor (52.9%), dyskinesia (66.7%), and myoclonus (40%)." (PMID 36441344, 2023). "Despite this connection to parkinsonism, we have not found any reports or cases that describe a PD patient with a heterozygous rare variant in the SPG11 gene." (PMID 38153678, 2024). "A Japanese neuropathological study of two patients with SPG11 showed depigmentation of the substantia nigra and their findings that motor neuron degeneration and parkinsonism in SPG11 patients is related to either TDP-43 pathology or TDP-43–negative neuronal cytoplasmic inclusions." (PMID 38035585, 2023). "The exact mechanisms linking SPG11 and parkinsonism are not yet fully understood." (PMID 37648940, 2023).
Parkinsonism (continued). "Neuroimaging studies have provided valuable insights into SPG11-related parkinsonism." (PMID 37648940, 2023). "This is highlighted by a recent study which showed that disruption of presynaptic dopaminergic pathways was a widespread phenomenon in individuals with SPG11 mutations, even without clinical manifestations of parkinsonism." (PMID 33646413, 2021). "A case study of SPG11 also reported some response of parkinsonism to levodopa." (PMID 30627115, 2018). "Additionally, cognitive impairments and psychiatric symptoms, including depression and anxiety, may be more prevalent in individuals with SPG11 and parkinsonism." (PMID 37648940, 2023). "SPG11 typically presents with a complex phenotype comprising different signs: thin corpus callosum, intellectual disability, progressive cognitive decline, cerebellar ataxia, WMHLs (“ears of the lynx”), seizures, parkinsonism, tremors, macular lesions, polyneuropathy, amyotrophy, etc.." (PMID 36139378, 2022). "Mutations in SPG11 and SPG15 generally result in a complex form of HSP, which is distinguished by prominent thinning of the corpus callosum, but also includes other neurological complications such as retinal abnormalities, intellectual disability, mild ataxia and parkinsonism." (PMID 26085577, 2015). "However, recent evidence suggests that some patients with SPG11 may also develop parkinsonism." (PMID 37648940, 2023). "Despite Spastic paraplegia type 4 being the most frequent form of HSP, recent studies have shown the emergence of parkinsonism as one of the symptoms to investigate, especially in SPG7 and SPG11, two HSPs with autosomal recessive transmission." (PMID 37648940, 2023). "SPG48 patients have some clinical features similar to those of SPG11 or SPG15 patients, including spastic paraplegia, retinal abnormalities and parkinsonism, but the clinical spectrum of AP5Z1 patients is still being defined." (PMID 26085577, 2015). "Parkinsonism has previously been described in association with SPG7, SPG11, SPG15, SPG21, SPG35, SPG48, and SPG78,1, 2, 3, 4 but not with SPG30." (PMID 37635774, 2023). "Faber and colleagues examined in vivo the dopaminergic system in a cohort of 22 SPG11 patients in patients with and without parkinsonism through the 99mTc-TRODAT-1 SPECT." (PMID 37648940, 2023). "SPG11, the most common AR SPG with thinning of the corpus callosum, can present with parkinsonism." (PMID 38035585, 2023). "However, it is worth noting that other larger series of SPG11 patients did not report the occurrence of parkinsonism." (PMID 37648940, 2023). "However, they noted a universal reduction of DAT density among SPG11 patients compared to healthy controls, even in the absence of parkinsonism." (PMID 37648940, 2023). "Notably, a link between HSP and dystonia-parkinsonism was recently also described for other HSP subtypes, i.e. SPG11, SPG15 and genetically undetermined HSP forms, and Lewy body pathology has been present in individual HSPs cases with parkinsonism, with or without dystonia." (PMID 23814539, 2013).
Ataxia (14 papers, 2015 to 2025). Ataxia refers to impaired coordination of voluntary muscle movement. "SPG15 resembles the phenotype of SPG11 with possible thin corpus callosum, intellectual disability, cerebellar ataxia, seizures, retinal involvement, polyneuropathy, and amyotrophy." (PMID 36139378, 2022). "At the time of its introduction in 2016, six conditions (EPG5‐related Vici syndrome, WDR45‐related BPAN, SNX14‐related ataxia as well as SPG11‐, ZFYVE26‐, and TECPR2‐related spastic paraplegia) were included with the concept of congenital disorders of autophagy." (PMID 39420677, 2025). "And autosomal recessive SPG such as SPG7 and SPG11 can also present with ataxia." (PMID 38035585, 2023). "SPG7 (36.8%), SPG11 (20.4%), and SPG5 (6.3%) were the commonest genotypes among those manifesting with ataxia." (PMID 36441344, 2023). "HSP-MD with SPG7 had higher frequency of later onset during adulthood (82.9% vs. 8.5%), ataxia (OR = 12.6), extraocular movement disturbances (OR = 3.4) and seizure (OR = 3.7) compared to HSP-MD with SPG11." (PMID 36441344, 2023). "Similar to human patients affected by SPG11, KO mice developed a progressive spastic gait disorder with cerebellar ataxia during the course of the disease, while we did not observe a thinning of the corpus callosum, which is one of the main features of SPG11 patients." (PMID 26284655, 2015).
Intellectual disability (13 papers, 2012 to 2025). "Clinically, SPG11 is typically associated with complicated phenotypes, including intellectual disability, progressive cognitive decline, axonal neuropathy and cerebellar signs." (PMID 36247768, 2022). "The patients of HSP with nonsense variants in the SPG11 gene showed onset at their 10's, spasticity, and weakness in the lower limbs with extensor plantar responses, dysarthria, intellectual disability, and cognitive decline." (PMID 35036589, 2022). "The phenotype of SPG11 patients usually linked with mental retardation like learning difficulties in childhood or decline in intelligence quotient (IQ) Score." (PMID 31289639, 2019). "The MMSE scores of the subjects were slightly lower for age and education, which is in line with the fact that intellectual disability is a frequent feature of SPG11-HSP." (PMID 37396771, 2023). "Another Chinese family with ARHSP-TCC was reported previously, the index patient presented with prominent intellectual disability rather than spasticity had different compound heterozygous mutations of SPG11." (PMID 27256065, 2016). "In patients who suffer from mental retardation, SPG11 may be responsible in UMN-dominant cases and FUS may be responsible in LMN-dominant cases." (PMID 26213621, 2015).
amyotrophic lateral sclerosis (9 papers, 2019 to 2025). Amyotrophic lateral sclerosis (ALS) is a neurodegenerative disease characterized by progressive muscular paralysis reflecting degeneration of motor neurons in the primary motor cortex, corticospinal tracts, brainstem and spinal cord. "Mutations of the SPG11 gene have been reported for other phenotypes, namely, Charcot-Marie-Tooth disease and amyotrophic lateral sclerosis." (PMID 35036589, 2022). "There is a phenotypic and neuropathological overlap between SPG11 (also termed ALS5) and amyotrophic lateral sclerosis." (PMID 36432490, 2022). "Of note, accumulation of insoluble cytoplasmic TDP-43 (the histopathological hallmark of amyotrophic lateral sclerosis) was also described in a post mortem case of SPG11, and the clinical overlap of SPG11 with amyotrophic lateral sclerosis has been described before." (PMID 35906604, 2022).
Dystonia (8 papers, 2013 to 2024). An abnormally increased muscular tone that causes fixed abnormal postures. "Patients IV:4 and V:7, though displaying some symptoms including spasticity or dystonia similar to their affected cousins did not have the SPG11 deletion allele, thus demonstrating intrafamilial genetic heterogeneity and indicating a separate cause of their phenotype." (PMID 38906889, 2024). "One of our SPG11 patients had pure HSP, and two had a complex phenotype with symptoms such as cognitive problems, dysgenesis of corpus callosum, periventricular WMHLs, dysarthria, tremors, and dystonia." (PMID 36139378, 2022).
axonal neuropathy (5 papers, 2014 to 2023). Any nerve disorder affecting the axon of a nerve. "The causative mutations were found in two sisters with complex HSP consistent with SPG11, associated with the late manifestation of severe axonal neuropathy." (PMID 27544499, 2016). "Although neuropathy is occasionally present in SPG11, in our SPG11 patients reported here it was particularly severe, highlighting the association of axonal neuropathy with SPG11 and the late manifestation of axonal peripheral nerve damage." (PMID 27544499, 2016). "Furthermore, we extend the findings that mutations in SPG11 are the cause of a spectrum of clinical features including the late manifestation of severe axonal neuropathy." (PMID 27544499, 2016). "An interesting aspect of the two SPG11 families discussed here is the initial clinical presentation as complex HSP with a later development of an axonal neuropathy clinically and electrophysiologically." (PMID 27544499, 2016). "In the past, axonal neuropathy has been infrequently associated with complex HSP and SPG11 mutations, although this is usually mild." (PMID 27544499, 2016). "The abundance of pleomorphic membranous material in suralis nerve biopsies of SPG11 patients is characteristic for a severe axonal neuropathy." (PMID 24794856, 2014).
cognitive decline (5 papers, 2015 to 2022). "SPG11‐associated HSP are often characterized by early‐onset, lower limbs spasticity, dysarthria, cognitive decline, peripheral neuropathy, and thin corpus callosum." (PMID 33638609, 2021).
juvenile amyotrophic lateral sclerosis (5 papers, 2012 to 2022). Juvenile amyotrophic lateral sclerosis (JALS) is a very rare severe motor neuron disease characterized by progressive upper and lower motor neuron degeneration causing facial spasticity, dysarthria, and gait disorders with onset before 25 years of age. "Interestingly, mutations in SPG11 can also cause other disorders, such as juvenile amyotrophic lateral sclerosis (ALS5), juvenile Parkinsonism, and autosomal recessive axonal Charcot-Marie-Tooth disease." (PMID 27256065, 2016). "SPG11 mutations can cause autosomal recessive hereditary spastic paraplegia (ARHSP) and juvenile amyotrophic lateral sclerosis (JALS)." (PMID 32383541, 2020).
paraplegia (5 papers, 2014 to 2024). Complete paralysis of the lower half of the body including both legs, often caused by damage to the spinal cord. "For the present study, we selected SPG11 patients with a spastic paraplegia phenotype and severe neuropathy." (PMID 34326717, 2021). "Coincided with previous reported patients, case 1 in our study presented typical SPG11 phenotype with spastic paraplegia and mental retardation." (PMID 31289639, 2019). "Interestingly, within the SPG11–HSP cohort, there was a positive correlation of IL-6 levels to disease severity as measured by the SPRS (Spastic Paraplegia Rating Scale)." (PMID 38305941, 2024). "The lack of research on the role of circRNA spastic paraplegia 11 (circ-SPG11) results in conducting this study." (PMID 34140036, 2021). "The putative Rab7 interactors that we did not test include Drosophila orthologs of Spg11 and Spg15, human spastic paraplegia proteins that form a complex on late endosomes." (PMID 25453831, 2014). "A further two Rabs showed strong and specific interactions with membrane traffic machinery that we did not validate because of a lack of suitable reagents: Rab26 with the spastic paraplegia proteins Spg11 and Spg15 (also found with Rab7), and Rab35 with the Rab GEF Sbf (SBF1/2 in humans)." (PMID 25453831, 2014).
autosomal recessive spastic paraplegia (4 papers, 2014 to 2024). "Examples include SPG11 (MIM# 610844) associated with autosomal recessive spastic paraplegia, RAB3GAP2 (MIM# 609275) linked to autosomal recessive Marsolf syndrome, and NPHP4 (MIM# 607215) linked to autosomal recessive nephronophthisis." (PMID 35330423, 2022). "Variants in the SPG11 gene are most commonly associated with autosomal recessive spastic paraplegia, although homozygous variants have been recently identified in juvenile ALS, and heterozygous missense variants in sALS." (PMID 31475037, 2019).
Charcot-Marie-Tooth disease (4 papers, 2018 to 2022). An inherited degenerative disorder involving the peripheral nerves. "SPG11 mutations are a major cause of AR-HSP-TCC, but may also cause AR Charcot-Marie Tooth disease." (PMID 33646413, 2021).
dementia (4 papers, 2019 to 2021). Loss of intellectual abilities interfering with an individual's social and occupational functions. "All evaluated cognitive functions were altered in patients with CTX (2/4 with dementia) and SPG11 (all with dementia) patients." (PMID 31231294, 2019).